BICD2 (BICD cargo adaptor 2)
Diseases named in the same sentence as BICD2 in open-access papers (continued):
Sharing a sentence is not in itself a finding about the gene and the disease.
breast carcinoma (1 paper, 2023). "No variants were significantly associated with breast cancer risk in UKBiobank after correction for multiple testing, but variants in BICD2 (p = 0.03) and TPPP2 (p = 0.02, OR = 1.95) were independently significant." (PMID 38136396, 2023). "Variants in BICD2 (six cases), FBN1 (four cases), CSGALNACT1 (one case), and ZNF841 (one case) were observed in at least one UKBiobank breast cancer case, but not in any controls." (PMID 38136396, 2023).
distal arthrogryposis (1 paper, 2018). A muscle tissue disease characterized by congenital joint contractures of hand and feet. "Expression of several genes linked to motor neuronopathy and familiar amyotrophic lateral sclerosis (EPHA4, IGHMBP2, VAPB, BICD2, and DYNC1H1) or distal arthrogryposis (MYH8, ZC4H2, MUSK, RAPSN) were significantly upregulated or downregulated." (PMID 29727687, 2018).
distal myopathy (1 paper, 2021). Distal myopathy refers to a group of muscle diseases which share the clinical pattern of predominant weakness and atrophy beginning in the feet and/or hands. "Other allelic neurological disorders with the same gene associations are ataxia with oculomotor apraxia (SETX), HSP (ALS2, SPG11, ERLIN1, and DDHD1), JPLS (ALS2), dHMN (SIGMAR1), distal myopathy (GNE), and distal SMA (BICD2)." (PMID 34946884, 2021).
distal spinal muscular atrophy (1 paper, 2021). "Several studies have reported BICD2 gene mutations in patients with distal spinal muscular atrophy (SMA)." (PMID 34946884, 2021).
Emery-Dreifuss muscular dystrophy (1 paper, 2026). Emery-Dreifuss muscular dystrophy (EDMD) is characterized by muscular weakness and atrophy, with early joint contractures and cardiomyopathy. "Several mutations of Nesprin-1 and 2 that cause Emery-Dreifuss muscular dystrophy are found in the motor-recruiting domain and may alter interactions with kinesin-1 and BicD2/dynein, consistent with the abnormally positioned nuclei found in patients with this disease." (PMID 41770881, 2026).
gastric cancer (1 paper, 2022). A primary or metastatic malignant neoplasm involving the stomach. "In addition to LRRFIP2, CCDC50, another splicing candidate of ESRP1, also showed skipping exon event and BICD2 showed retained intron event occurring in gastric cancer cells depending on the expression of ESRP1." (PMID 36307405, 2022).
heart failure (1 paper, 2022). Inability of the heart to pump blood at an adequate rate to meet tissue metabolic requirements. "Considering the possible interaction between LMNA and BICD2 and the heart failure symptoms of BICD2 mutant patients, we hypothesized that the homozygous variant (NM_001003800.1:c.2429G > A) in the C-terminal region of BICD2 would be a candidate DCM-causative variant in this family." (PMID 36068540, 2022).
lung carcinoma (1 paper, 2009). "BICD2, CDA, NMNAT2, SERPINB13, and TOX3 have no specificity to either AC or SCC but to lung cancer." (PMID 19761563, 2009).
nephrolithiasis (1 paper, 2023). The presence of a calculus in the pelvis of the kidney; this is most often composed of mineral salts and proteins. "Considering the stimulatory effects of BICD2 on ferroptosis, our data thus provide new insight into BICD2 action in the process of nephrolithiasis and other inflammatory diseases." (PMID 37833251, 2023).
neuroblastoma (1 paper, 2019). Neuroblastoma (NB) is the most common solid, extracranial childhood tumor. "We investigated the effect BICD1 or BICD2 silencing on HIF1α nuclear translocation in SK-N-MC neuroblastoma cell line as a non-MSC cell model." (PMID 30464225, 2019).
pancreatic cancer (1 paper, 2021). "BICD2 suppressed by miR-340 is up-regulated in pancreatic cancer." (PMID 33928106, 2021).
Vocal cord paralysis (1 paper, 2024). A loss of the ability to move the vocal folds. "However, vocal cord paralysis has also been reported in patients with distal HMN due to SLC5A7 mutation and SMA-LED2 due to BICD2 mutation." (PMID 39457418, 2024).
infection (5 papers, 2020 to 2025). The state of being infected such as from the introduction of a foreign agent such as serum, vaccine, antigenic substance or organism. "In cells expressing HA-mCherry, knockdown of BICD2 blocked infection as expected (first to second bar)." (PMID 38829892, 2024). "Our results reveal the molecular basis by which the dynein motor captures HPV to promote infection and identify this virus as a novel cargo of the BICD2 dynein adaptor." (PMID 38829892, 2024). "Together, these results clarify the mechanism by which dynein recruits HPV to promote infection and reveal the incoming viral particle as a novel cargo for BICD2." (PMID 38829892, 2024). "In 2017, the Campbell laboratory showed that BicD2 is an essential host factor required for infection." (PMID 32344581, 2020). "Having established that the interaction between ScaC and BICD2 is sufficient to elicit microtubule-based transport in cells and in vitro, we asked whether it is required for O. tsutsugamushi motility during infection." (PMID 40610402, 2025). "Further work is needed to understand the relationship between HIV-1 capsid binding to BicD2 and whether this is important to infection and motility." (PMID 40532013, 2025). "Here we show that the dynein cargo adaptor BICD2 binds to the HPV L2 capsid protein during entry, recruiting HPV to dynein for transport of the virus along the endosome-TGN/Golgi axis to promote infection." (PMID 38829892, 2024). "In this manuscript, we demonstrate that the dynein cargo adaptor BICD2 interacts directly with the HPV L2 capsid protein, ferrying the virus from the endosome to the TGN/Golgi in order to promote infection." (PMID 38829892, 2024). "Depletion of any of the adaptors decreased HPV16.L2F infection to a varying extent when compared to cells treated with the scrambled (Scram) siRNA, with KD of BICD2 and BICDR1 blocking infection most severely." (PMID 38829892, 2024). "We show that ScaC is sufficient to engage dynein-based motility in the absence of other bacterial proteins and that BICD1 and BICD2 are required for efficient movement of O. tsutsugamushi during infection." (PMID 40610402, 2025). "Together, these data demonstrate that loss of BICD2 inhibits infection by several HPV types but does not globally compromise cellular integrity, suggesting BICD2 serves a specific function during HPV infection." (PMID 38829892, 2024). "Expression of HA-WT BICD2* in cells transfected with the scrambled control siRNA did not increase infection (third bar)." (PMID 38829892, 2024). "Because loss of BICD2 or BICDR1 resulted in the most severe phenotype in HeLa cells, we also knocked down each of these proteins in HaCaT cells and found that infection was also impaired in these cells without damaging the cellular membrane." (PMID 38829892, 2024). "We then evaluated the importance of BICD2 and BICDR1 in promoting infection of different HPV types." (PMID 38829892, 2024). "As a control, we show that this inability to restore infection is not because A/V BICD2 is globally misfolded because it can bind to HPV L2 during entry, suggesting that cargo-binding remains intact for this BICD2 mutant." (PMID 38829892, 2024). "Using a different strategy, silencing by siRNAS, they demonstrated that not only BicD2, but also dynactin backbone complex (ACTR1 and DCTN2/DCTN3) facilitate the transport and infection of HIV-1, confirming that BicD2 is the adaptor between HIV-1 PIC and dynein." (PMID 32344581, 2020). "Importantly, expression of HA-WT BICD2* in BICD2 KD cells largely restored infection (fourth bar), but expression of HA-A/V BICD2* in BICD2 KD cells did not (fifth bar)." (PMID 38829892, 2024). "Because Nesprin-2 and RanBP2 are both cytoplasmic-facing nuclear membrane proteins that bind to the BICD2-dynein motor complex, we hypothesized that one (or both) of these host factors may be responsible for capturing SV40 to facilitate nuclear entry and infection." (PMID 36067270, 2022).
infection (continued). "Importantly, we identified the motor-binding domain of Nesprin-2 as critical for infection, consistent with the hypothesis that this domain is used to recruit SV40 to the nuclear membrane via the BICD2-dynein motor complex." (PMID 36067270, 2022). "In the absence of BICD2 function, HPV accumulates in the endosome and TGN and infection is inhibited." (PMID 38829892, 2024). "KD of BICD2 (but not BICDR1) inhibited infection of HPV5 and HPV18, suggesting that BICD2 is critical for infection of multiple HPV types." (PMID 38829892, 2024).
neurological diseases (5 papers, 2015 to 2024). "Here, we present one patient with a known and six patients with novel BICD2 missense variants, further characterizing the molecular landscape of this heterogenous neurological disorder." (PMID 37047781, 2023). "The dynein-adaptor protein BICD2 is associated with a spectrum of human neurological diseases, including malformations of cortical development." (PMID 31655624, 2019). "Mutations in dynein and its regulatory factors, including the dynactin subunit p150Glued, BICD2 and Lis-1, are associated with several human nervous system disorders, including cortical malformation and motor neuropathy." (PMID 26578860, 2015).
inflammatory myopathy (3 papers, 2023 to 2025). "The most prominent clinical feature of BICD2-associated myopathy is an atrophic paresis of the leg muscles, which was pronounced in the distal leg muscles of patients p1, p3, p4, p5, and p6 and in the proximal and distal leg muscles of p2." (PMID 37047781, 2023). "Indeed, BET1 (SNARE protein involved in the docking process of ER-derived vesicles with the cis-Golgi membrane) was moreover increased in the muscle tissue of patients with BICD2-associated myopathy (p1, p3, and p5)." (PMID 37047781, 2023). "Recently, a murine model of BICD2-associated myopathy has been published." (PMID 37047781, 2023). "However, the single specificity for anti-BICD2 antibodies is associated with a unique phenotype of SSc, related to the development of ILD, inflammatory myopathy, and dcSSc." (PMID 35716254, 2023). "In conclusion, anti-BICD2 could be added to the list of SSc-associated antibodies capable of identifying a clinical profile characterized by ILD and inflammatory myopathy in SSc." (PMID 35716254, 2023).
tumor (3 papers, 2017 to 2022). "Moreover, in vivo study revealed that DT-13 combined with NVB significantly suppressed tumor growth in nude mice xenograft model, meanwhile, the changes of FOXM1 and BICD2 in tumor tissues further demonstrated the molecular mechanisms in vitro." (PMID 28542137, 2017). "In addition, in the tumor tissues of combination group, the expression of MPM2 was also increased, whereas FOXM1 and BICD2 were reduced, and the quantity of Tunel-positive cells was dramatically induced by combination treatment." (PMID 28542137, 2017). "In addition, in vivo study revealed that DT-13 combined with NVB significantly suppressed tumor growth in nude mice xenograft model, and downregulated the expression of FOXM1 and BICD2 in tumor tissues, which was consistent with in vitro study." (PMID 28542137, 2017).
BICD2 also shares sentences with these, for which no sentence is quoted: brain malformations (2 papers); neuromuscular disease (2); arthrogryposis (1); arthrogryposis multiplex congenita (1); Atrophy (1); band heterotopia (1); Cerebellar hypoplasia (1); ciliopathy (1); dilated cardiomyopathy (1); juvenile ALS (1); kidney disease (1); microcephaly (1); neurodegenerative disease (1); neurogenic muscular atrophy (1); non-small cell lung carcinoma (1); osteoporosis (1); Pachygyria (1); pulmonary arterial hypertension (1); spinal muscular atrophy, type II (1).